MMP25 (matrix metallopeptidase 25)
Diseases named in the same sentence as MMP25 in open-access papers (continued):
Sharing a sentence is not in itself a finding about the gene and the disease.
cancer (16 papers, 2005 to 2025). A tumor composed of atypical neoplastic, often pleomorphic cells that invade other tissues. "Further, MMP25 may be strongly associated with cancer development and the progression of other diseases by affecting immune functions." (PMID 36685840, 2022). "Furthermore, high expression levels of MMP25 were associated with many pathways in cancer, for instance, KRAS signaling pathway, apoptosis, PI3K/AKT/mTOR signaling pathway, and JAK/STAT signaling pathway." (PMID 32850314, 2020). "Taken together, it is possible that the regulation of cancer-associate genes and signaling pathways may be involved in the regulatory role of MMP25 in the clinical stages and prognosis in HNSCC." (PMID 32850314, 2020). "MMP-25 (MT6-MMP), encoded on chromosome 16, is a GPI-anchored enzyme expressed in leukocytes and certain cancers." (PMID 41281748, 2025). "The precancerous microenvironment showed significant upregulation of zebrafish orthologues for MMP25 and CTSB, while orthologues for multiple MMPs and CTSs were upregulated in the cancer microenvironment." (PMID 39511408, 2025). "Our results show that TGF-β/TNF-α combined treatment of the cancer cells synergistically increased the expression of MMP-2 and MMP-25 when we compared either treatment of TGF-β or TNF-α." (PMID 39351229, 2024). "We here demonstrate that, though hypermethylation of certain CpGs in promoter regions of the MMP2, MMP23B, MMP24, MMP25, and MMP28 genes is cancer specific, it lacks independent biological or clinical value, being rather a function from HER2 activation." (PMID 32397602, 2020). "IHC analysis of MMP-25 protein expression in colorectal tissue sections shows MMP-25 is strongly expressed on the leading edge of tumours and positively correlates to an invasive cancer." (PMID 20809987, 2010). "In healthy systems, MMP-25 can act as both an extra-cellular protease and an activator of some secreted pro-MMPs; however, MMP-25 is also over-expressed in certain cancers and appears to play a role in their progression." (PMID 20809987, 2010). "Specific MMPs, including MMP2, MMP9, MMP11, MMP14, MMP15, MMP25, and MMP28, were increased in this region, indicating their distinct roles in the tumor microenvironment and confirming the importance of understanding the effects of cysteamine on specific MMPs in GBM cancer models." (PMID 38893149, 2024). "Proteases present in malignant tumours but not in normal skin included: PGC, BAP1, caspase-8, F13A1, MMP11, MMP23, MMP25, MMP26 and granzyme-A." (PMID 35327667, 2022).
tumor (15 papers, 2010 to 2024). "The expression of MMP17 and MMP25 was significantly associated with the depth of tumor invasion, lymph node metastasis and serous membrane involvement (P<0.05), but not with patient age and gender, or lesion length, site and histological grade (P>0.05)." (PMID 25621036, 2015). "Moreover, our analysis suggested that immune infiltration levels and diverse tumor-associated pathways were correlated with levels of MMP25 expression." (PMID 32850314, 2020). "Moreover, the expression of MMP25 potentially contributes to the regulation of tumor-associated pathway and oncogenes." (PMID 32850314, 2020). "This analysis prompted a focus on specific MMPs more distinctly expressed in CC2, such as MMP2, MMP9, MMP11, MMP14, and MMP25, suggesting their potential role in tumor invasion and their clinical relevance as potential therapeutic targets." (PMID 38893149, 2024). "For instance, upregulation of most cathepsins, CAPN1 and 2, MEP1A, and MMP25, exhibited a major correlation with poor prognostic features such as recurrence, perineural invasion, nodal extracapsular extension, and tumor size." (PMID 33578082, 2021). "In the present study, the high expression level of MMP25 showed a strong relationship with the immune scores between tumor tissues and normal tissues, as well as in different clinical stages." (PMID 32850314, 2020). "In our study, abnormal hypermethylation of promoter CpG dinucleotides of the MMP2, MMP23B, MMP24, MMP25, and MMP28 was associated with HER2-positive tumor status, and, to a different extent, with CpG island hypermethylated epigenomic BC subtype." (PMID 32397602, 2020). "Our work revealed that MMP-3 and MMP-25 high expression levels were correlated with higher OSC tumor stage, providing further evidence of these MMPs in OSC progression." (PMID 31406154, 2019). "Since the depth of tumor invasion, lymph node metastasis and serous membrane involvement were closely associated with tumor progression, MMP17 and MMP25 were associated with tumor progression." (PMID 25621036, 2015). "In addition, MMP25 expression significantly correlated with the regulation of various oncogenes and tumor-related pathways." (PMID 32850314, 2020). "It was suggested that MMP-25 may be important for tumor cell invasion because elevated levels are identified in the tumor progression process of invasive colon cancer." (PMID 31886121, 2019). "Indeed, Fisher’s exact test supports a statistically significant association of abnormal methylation of MMP24 and MMP25 promoters in tumor samples with their attribution to the hypermethylated BC subtype with p = 0.033 for MMP24 and p = 0.002 for MMP25." (PMID 32397602, 2020). "Also, MMP-25 reduces the levels of alpha-1 proteinase inhibitor, stimulating the ECM degradation and the subsequent tumor invasion and migration." (PMID 31886121, 2019). "We could see that about half MMPs are highly expressed in tumor tissues as compared with normal tissues, including MMP9, MMP10, MMP11, MMP12, MMP15, MMP25, MMP26 (all, P<0.05), while some other MMPs decreased in tumor tissues, including MMP2, MMP14, MMP16, MMP24, MMP28(all, P<0.05)." (PMID 32669958, 2020).
bacterial infection (2 papers, 2017 to 2023). "MMP25 is activated when cleaved by extracellular proteinases in response to bacterial infection or inflammation and is believed to inactivate the alpha-1 proteinase inhibitor." (PMID 28814982, 2017).
MMP25 also shares sentences with these, for which no sentence is quoted: brain tumors (3 papers); medulloblastoma (2); acute respiratory distress syndrome (1); asthma (1); atherosclerosis (1); autism (1); conjunctivitis (1); emphysema (1); gastric tumors (1); glioblastoma (1); glioma (1); lymph node metastasis (1); metastatic melanoma (1); nasal polyps (1); pancreatic cancer (1); prostate carcinoma (1); rectal cancer (1); Stroke (1); uveitis (1).